PHF5A (PHD finger protein 5A)
Description:
Component of the 17S U2 SnRNP complex of the spliceosome, a large ribonucleoprotein complex that removes introns from transcribed pre-mRNAs. The 17S U2 SnRNP complex (1) directly participates in early spliceosome assembly and (2) mediates recognition of the intron branch site during pre-mRNA splicing by promoting the selection of the pre-mRNA branch-site adenosine, the nucleophile for the first step of splicing. Within the 17S U2 SnRNP complex, PHF5A is part of the SF3B subcomplex, which is required for 'A' complex assembly formed by the stable binding of U2 snRNP to the branchpoint sequence in pre-mRNA. Sequence independent binding of SF3A and SF3B subcomplexes upstream of the branch site is essential, it may anchor U2 snRNP to the pre-mRNA. Also acts as a component of the minor spliceosome, which is involved in the splicing of U12-type introns in pre-mRNAs. Also involved in elongation by RNA polymerase II as part of the PAF1 complex (PAF1C) (By similarity). PAF1C is required for maintenance of embryonic stem cell (ESC) self-renewal and cellular reprogramming of stem cells (By similarity). Maintains pluripotency by recruiting and stabilizing PAF1C on pluripotency genes loci, and by regulating the expression of the pluripotency genes (By similarity). Regulates the deposition of elongation-associated histone modifications, including dimethylated histone H3 'Lys-79' (H3K79me2) and trimethylated histone H3 'Lys-36' (H3K36me3), on PAF1C targets, self-renewal and pluripotency genes (By similarity). Regulates RNA polymerase II promoter-proximal pause release of the PAF1C targets and self-renewal genes, and the levels of elongating ('Ser-2' phosphorylated) RNA polymerase II in their gene bodies (By similarity). Regulates muscle specification in adult stem cells by stabilizing PAF1C in chromatin to promote myogenic differentiation (By similarity). Acts as a transcriptional regulator by binding to the GJA1/Cx43 promoter and enhancing its up-regulation by ESR1/ER-alpha (By similarity).
Synonyms: SF3b14b; MGC1346; INI; bK223H9.2; Rds3; SAP14b; SF3B7
Tractability: Small molecule: a structure with a bound ligand is known. PROTAC: ubiquitination databases record sites on it; its protein half-life has been measured.
Gene: Protein-coding gene on chromosome 22 (41,459,705 to 41,468,711, reverse strand). Ensembl gene ENSG00000100410.
Subcellular location: Nucleus; Nucleus speckle
Subcellular location (Human Protein Atlas): Nucleoplasm
Pathways (Reactome):
Metabolism of RNA: mRNA Polyadenylation; mRNA Splicing - Major Pathway
Chromatin organization: CHD1 and CHD2 subfamily
Disease: Dengue Virus-Host Interactions
Gene Ontology:
Molecular function: protein binding; RNA binding; zinc ion binding
Biological process: mRNA splicing, via spliceosome; positive regulation of DNA-templated transcription; spliceosomal snRNP assembly; spliceosome conformational change to release U4 (or U4atac) and U1 (or U11); U2-type prespliceosome assembly; stem cell differentiation
Cellular component: nucleoplasm; nucleus; precatalytic spliceosome; spliceosomal complex; U12-type catalytic step 2 spliceosome; U12-type precatalytic spliceosome; U12-type spliceosomal complex; U2 snRNP; U2-type catalytic step 1 spliceosome; U2-type precatalytic spliceosome; U2-type spliceosomal complex; catalytic step 2 spliceosome; nuclear speck; nuclear matrix
Genetic constraint (gnomAD): Loss-of-function variants: 0 observed, 14.61 expected, observed/expected ratio (o/e) 0, 90% interval 0 to 0.2. The upper end of that interval is the gene's LOEUF score, 0.2, which puts it in group 1 of 6, group 1 being the genes least tolerant of losing a copy. Missense variants: 21 observed, 140.8 expected, observed/expected ratio (o/e) 0.15, 90% interval 0.1 to 0.22. Synonymous variants: 52 observed, 47.14 expected, observed/expected ratio (o/e) 1.1, 90% interval 0.88 to 1.39.
Homologues: Orthologues: chimpanzee PHF5A (100% identical), guinea pig PHF5A (100% identical), macaque PHF5A (100% identical), mouse Phf5a (100% identical), pig PHF5A (100% identical), rabbit PHF5A (100% identical), tropical clawed frog phf5a (100% identical), zebrafish phf5a (100% identical), Drosophila melanogaster Phf5a (95% identical), rat Phf5a (95% identical), Caenorhabditis elegans phf-5 (90% identical), dog PHF5A (68% identical).
Diseases named in the same sentence as PHF5A in open-access papers:
PHF5A is named in the same sentence as 63 diseases in open-access papers, as found by Europe PMC text mining. Sharing a sentence is not in itself a finding about the gene and the disease. The quoted sentences say what the papers report.
breast carcinoma (12 papers, 2019 to 2025). "Recent studies have linked an upregulation of PHF5A with the development of different cancer types, such as lung adenocarcinoma, breast cancer, and glioblastoma." (PMID 39212334, 2025). "PHF5A, identified as a crucial splicing factor in tumor progression, has been implicated in breast cancer’s aggressive behavior." (PMID 38813086, 2024). "PHF5A was identified as a potential epigenetic inhibitor of apoptosis that was over-expressed in breast cancer with simultaneous association to deprived survival." (PMID 37483794, 2023). "One in vivo screen identified PHD finger protein 5 A (PHF5A) as a regulator of migration, survival, and breast cancer formation through SF3b spliceosome stability, suppressing apoptosis." (PMID 40650785, 2025). "Further investigating this observation, we were able to show that the loss of PHF5A results in dysregulation of splicing of the anti‐apoptotic gene FASTK, which has already been shown in breast cancer cells." (PMID 39212334, 2025). "This modification, particularly pronounced in breast cancer, underscores PHF5A’s role in undermining apoptosis, highlighting its therapeutic potential against cancer’s advance." (PMID 38813086, 2024). "PHF5A is reported to contribute well as a proto-oncogene in the progression of different malignancies including breast cancer, lung cancer, gastric cancer, hepatocellular carcinoma, endometrial adenocarcinoma, etc.." (PMID 37483794, 2023). "In breast cancer, PHF5A is essential for cancer cell proliferation, migration, and tumour formation in part through alternative splicing of FASTK." (PMID 37434235, 2023). "The PHF5A expression is elevated in many types of cancer, such as breast cancer, colorectal cancer, gastric cancer and hepatocellular carcinoma." (PMID 37845358, 2023). "Currently, PHF5A participation in the incidence and proliferation of numerous cancers like lung cancer, breast cancer, colorectal tumors, endometrial tumors, squamous cell carcinoma, oral cell carcinoma, and hepatocellular carcinoma has been elucidated." (PMID 37483794, 2023). "With regard to tumours, PHF5A is overexpressed in lung cancer, breast cancer, colorectal cancer and hepatocellular carcinoma and promotes malignant tumour biological progression associated with the NF-κB pathway, RhoA/ROCK pathway, and activation of HDAC8." (PMID 37434235, 2023). "Zheng and his colleges demonstrated that upregulation of PHF5A leads to poor survival of breast cancer via inhibiting Fas-mediated apoptosis." (PMID 30766880, 2019). "Zheng et al20 demonstrated that PHF5A acted as an oncogene to promote breast cancer progression by inhibiting apoptosis." (PMID 30932358, 2019). "Furthermore, it is reported that PHF5A promotes breast cancer and lung adenocarcinoma as a novel oncogene through inhibiting apoptosis." (PMID 38429756, 2024). "In breast cancer, PHF5A expression exhibited a high level and correlated with poor survival." (PMID 38429756, 2024). "PHF5A was initially described as an essential splicing factor actively participating as an oncoprotein in the progression of breast cancer and might be pondered as a potential therapeutic drug target." (PMID 37483794, 2023). "Plant homeodomain (PHD)–finger domain protein PHF5A, a critical splicing factor involved in AS, has been demonstrated to play an oncogenic role in glioblastoma multiforme and breast cancer, but its biological function in lung cancer remains unclear." (PMID 30932358, 2019). "These genes included BPTF, PHF5A, and SPG7 in cancer of female genital organs, as well as FGF10, NFIX, and SCAP in breast cancer." (PMID 38409266, 2024). "In addition, the elevated expression of another component of SF3b complex, PHD finger 5A (PHF5A)/SF3B7, is observed in breast tumors, and high PHF5A expression correlates with poor disease-free survival in breast cancer patients." (PMID 32106418, 2020).
lung adenocarcinoma (9 papers, 2018 to 2025). A carcinoma that arises from the lung and is characterized by the presence of malignant glandular epithelial cells. "PHD Finger Protein 5A (PHF5A), on the other hand, plays a key role in the occurrence and development of lung adenocarcinoma and glioblastoma." (PMID 41268576, 2025). "In lung adenocarcinoma, PHF5A functioned as an oncoprotein to inhibit cisplatin-induced apoptosis, facilitate cell proliferation, migration and invasion, as well as G0/G1 cell cycle progression." (PMID 38429756, 2024). "Research on lung adenocarcinoma has indicated that PHF5A expression is positively correlated with the T stage as well as lymph node metastasis." (PMID 37845358, 2023). "Here the upregulated expression of PHF5A resulting from the aberrant regulation of multiple signaling pathways was correlated with enhanced proliferation and progression of lung adenocarcinoma cells in comparison to adjacent non tumor tissues." (PMID 37483794, 2023). "The current study explored the oncogenic role of PHF5A in the pathogenesis of lung adenocarcinoma via the regulation of numerous signaling pathways including IGF-1." (PMID 37483794, 2023). "In human lung adenocarcinoma H1299 and A549 cells, the knockdown of PHF5A or a small molecule inhibitor of PHF5A (pladienolide) induces the alternative splicing of many cell cycle-regulated genes and apoptosis-associated genes, including BCL-RAMBO." (PMID 36589739, 2022). "PHF5A is highly upregulated in lung adenocarcinoma and PHF5A knockdown can result in reducing cell proliferation and cell cycle arrest and contributes to cell apoptosis." (PMID 30766880, 2019). "Upregulation of PHF5A was negatively correlated to the overall survival (OS) of lung adenocarcinoma (LUAD) patients." (PMID 30932358, 2019). "The purpose of this study was to determine the functional relevance and therapeutic potential of PHF5A in lung adenocarcinoma (LAC)." (PMID 29566713, 2018). "However, pladienolide, a small molecular inhibitor of PHF5A, inhibited lung adenocarcinoma cell proliferation in a dose-dependent manner and induced alternative splicing changes." (PMID 38429756, 2024). "Additionally, PHF5A has been found to be necessary for the invasion and migration of lung adenocarcinoma cells." (PMID 37845358, 2023). "PHF5A silencing or depletion provoked vice versa outcomes indicated by promoted apoptosis and cell cycle arrest coupled with reduced invasion, migration, or proliferation of lung adenocarcinoma cells." (PMID 37483794, 2023). "PHF5A participates well in progression of different types of cancers including breast, lung, hepatocellular, lung adenocarcinoma and gastric tumors occurs through regulation/stimulation of numerous signaling pathways such as AKT/mTOR, NF- κB, IGF-1 and YAP signaling pathways." (PMID 37483794, 2023). "High expression PHF5A was associated with upregulated proliferation, invasion, and metastasis of cancer (LAUD) cells and prohibition of cisplatin provoked apoptosis with subsequent poor survival of lung adenocarcinoma patients." (PMID 37483794, 2023). "It is also reported that PHF5A played an oncogenic role via AS in lung adenocarcinoma." (PMID 32228507, 2020). "Presently identification of spliceosome and non-spliceosome-associated attributes of PHF5A needs great attention based on its key involvement in the pathogenesis of cancer malignancies including the prognosis of lung adenocarcinoma, endometrial adenocarcinoma, breast, and colorectal cancer." (PMID 37483794, 2023). "Correspondingly, potential inhibition of lung adenocarcinoma cells proliferation and pathogenesis via Pladienolide B indicated potential concentration-dependent anti-proliferative attributes with consequences quite similar to that of PHF5A silencing or knockdown." (PMID 37483794, 2023). "However, the molecular and biological functions of Phf5a in lung cancer, particularly lung adenocarcinoma (LAC), remain unknown." (PMID 29566713, 2018).
glioblastoma (8 papers, 2018 to 2025). The most malignant astrocytic tumor (WHO grade IV). "PHF5A knockdown in glioblastoma stem cells indicated prohibition of PHF5A-assisted splicing genes and associated U2 SnRP activity with consequent cell cycle arrest and viability loss." (PMID 37483794, 2023). "Moreover, genome-wide splicing alterations after PHF5A loss appear only in glioblastoma cells." (PMID 32488114, 2020). "Correspondingly, PHF5A silencing prevented the growth of conventional patient-originated glioblastoma stem cell xenografts along with the in-vivo prohibition of glioblastoma stem cells tumor growth." (PMID 37483794, 2023). "In glioblastoma, PHF5A facilitated the recognition of exons with unusual C-rich 3’ splice sites in multiple essential genes and enhanced alternative splicing to maintain glioblastoma stem cell expansion." (PMID 37434235, 2023). "Further studies could link the upregulation of PHF5A to increased progression of cancer entities, such as glioblastoma multiforme or colorectal cancer, because of inhibited splicing, supporting our findings." (PMID 39212334, 2025). "PHF5A also acts as a key regulator required for the enhancement of glioblastoma multiforme stem cells; identified using multigenome wide RNAi screens derived from patient glioblastoma multiform stem cells and compared to neutral stem cells and fibroblasts." (PMID 37483794, 2023). "The SF3b-complex protein PHF5A was required for glioblastoma cells to survive, but not neural stem cells (NSCs)." (PMID 32488114, 2020).
colorectal cancer (5 papers, 2023 to 2025). A primary or metastatic malignant neoplasm that affects the colon or rectum. "Up-regulation of PHF5A was associated with enhanced migration and invasion of tumor cells together with poor survival and disease-free clinical outcomes of patients with colorectal cancer." (PMID 37483794, 2023). "Numerous hitherto studies signified the role of PHF5A in the initiation and progression of the lung, breast, and colorectal cancers [35,36,]." (PMID 37483794, 2023). "Comparative analysis of PHF5A expression in colorectal cancer cells and normal paracancerous cells indicated its over-expression in tumor tissues." (PMID 37483794, 2023). "PHF5A could also promote colorectal cancer progression by alternative splicing of TEAD2." (PMID 37434235, 2023). "In particular, in colorectal cancer, PHF5A acetylation strengthened the interaction among U2 snRNPs and enhanced the alternative splicing-mediated upregulation of KDM3A to promote colorectal cancer tumorigenesis." (PMID 37434235, 2023).
non-small cell lung carcinoma (5 papers, 2018 to 2024). A group of at least three distinct histological types of lung cancer, including non-small cell squamous cell carcinoma, adenocarcinoma, and large cell carcinoma. "TCGA and tissue microanalysis indicated the significant over-expression of PHF5A in cancer cell lines upon investigation of the clinical and biological performance of PHF5A in NSCLC (non-small cell lung cancer)." (PMID 37483794, 2023). "PHD-finger domain protein 5A (PHF5A) is a highly conserved small transcriptional regulator also involved in pre-mRNA splicing; however, its biological functions and molecular mechanisms in non-small cell lung cancer (NSCLC) have not yet been investigated." (PMID 29566713, 2018).
hepatocellular carcinoma (4 papers, 2023 to 2024). A malignant tumor that arises from hepatocytes. "Progression of hepatocellular carcinoma was correlated to PHF5A-mediated activation of the NF-κB signaling pathway since PHF5A depletion indicated downregulation of the current/classical signaling pathway along with the prohibitory impact on tumor prognosis." (PMID 37483794, 2023). "Overexpression of PHF5A in hepatocellular carcinoma cells has also been reported with its depletion being associated with reduced invasion, migration, and propagation of hepatocellular carcinoma." (PMID 37483794, 2023). "For hepatocellular carcinoma (HCC), a previous study illustrated that elevated PHF5A expression facilitates invasion and migration via the NF-KB pathway, but comprehensive correlation analysis of PHF5A with tumor immunity and angiogenesis in HCC has not been performed." (PMID 39030507, 2024).
gastric cancer (3 papers, 2023). A primary or metastatic malignant neoplasm involving the stomach. "Overexpression of PHF5A along with T lymphocyte infiltration and reduced survival of patients displaying gastric cancer was noticed." (PMID 37483794, 2023). "High expression of PHF5A in gastric carcinoma cells (MGC 803 cells) specified promoted tumor pathogenesis attributed to stimulation of NF- κB signaling pathway while PHF5A knockdown presented negative consequences i.e. prohibition of gastric carcinoma cells proliferation, migration, and prognosis." (PMID 37483794, 2023).
lung carcinoma (3 papers, 2019 to 2023). "In lung cancer, PHF5A promoted cancer cell proliferation, invasion and migration by inducing genome-wide alternative splicing events." (PMID 37434235, 2023). "We concluded that PHF5A function as a global splicing factor affected the biological behavior of lung cancer cells by regulating the AS of many downstream genes, especially cell cycle–associated and apoptosis–associated genes." (PMID 30932358, 2019). "In the present study, we systematically analyzed the biological function and clinical relevance of PHF5A in non–small cell lung cancer (NSCLC)." (PMID 30932358, 2019). "Moreover, pladienolide, a small molecular inhibitor of PHF5A, inhibited lung cancer cell proliferation in a dose–dependent manner and induced similar downstream gene changes." (PMID 30932358, 2019). "Since PHF5A played an important role in lung cancer progression, we speculated whether PHF5A could act as a new drug target or whether an inhibitor of PHF5A could exert an antitumor effect." (PMID 30932358, 2019).
lymph node metastasis (3 papers, 2018 to 2023). "We also found that high PHF5A expression was associated with clinical parameters such as lymph node metastasis, smoking and alcohol consumption in TCGA data." (PMID 37434235, 2023). "Additionally, the elevated expression of PHF5A in ACC was found to be significantly associated with the presence of distant metastasis and an increased occurrence of lymph node metastasis." (PMID 37845358, 2023).